GABBR1 (gamma-aminobutyric acid type B receptor subunit 1)
Diseases named in the same sentence as GABBR1 in open-access papers (continued):
Sharing a sentence is not in itself a finding about the gene and the disease.
cancer (20 papers, 2011 to 2026). A tumor composed of atypical neoplastic, often pleomorphic cells that invade other tissues. "Of the other 16 genes, COL5A1, GABBR1, HACE1, EPHA7, and TRIP11 have well-documented associations with cancer." (PMID 30962767, 2019). "The expression level of GABBR1 also was negatively correlated with that of miRNAs in cancer tissues." (PMID 27230463, 2016). "This known biological function provides some a priori support for a possible functional role of GABBR1 in cancer development." (PMID 24367763, 2013). "However, there are few studies on the relationship between GABBR1 and cancer, and further exploration is needed." (PMID 35535346, 2022). "Gamma-aminobutyric acid type B receptor subunit 1 (GABBR1) encodes the G protein-coupled receptor that can form the heterodimer with GABAB receptor 2, which triggering the proliferation, differentiation and migration of cancer cells." (PMID 29933410, 2018). "In contrast to HCG9, GABBR1 encodes a G protein-coupled receptor that forms a heterodimer with GABAB receptor 2, thereby triggering downstream signaling events in the proliferation, differentiation, and migration of cancer cells." (PMID 24367763, 2013). "As a receptor component of the inhibitory GABAergic system that transduces GABA release into metabotropic signal transduction cascades, the up-regulation of GABBR1 may have a suppressive effect on the behavior of malignant tumors in NPC cancer cells." (PMID 21283797, 2011). "Thus it can be seen that GABBR1 methylation play a crucial role in various cancers." (PMID 29933410, 2018). "It would be interesting to follow our patients with NEPC, who displayed elevated GABBR1 and ENO2 gene expression levels, to evaluate the cancer progression." (PMID 29980692, 2018). "The GCNT2 gene has never been linked to cancer development, so we selected NEDD9 and GABBR1 as the most promising potential candidate genes." (PMID 21283797, 2011). "However, the study did not compare the GABBR1 transcript and protein expression levels between normal and cancer cell lines." (PMID 21283797, 2011). "However, three of the target genes, to our knowledge, are not described in relation to cancer or HBV infection (ACADSB, GABBR1, and PAPD5)." (PMID 25580300, 2014).
psychiatric disorder (8 papers, 2020 to 2026). A disorder characterized by behavioral and/or psychological abnormalities, often accompanied by physical symptoms. "For example, GABBR1 encodes GABA receptors involved in GABAergic neurotransmission, with central roles in AD and psychiatric disorders." (PMID 41299092, 2026). "Advances in high-throughput genomic technologies, particularly whole-exome sequencing, have uncovered hundreds of variants in the genes encoding the GBR subunits, GABBR1 and GABBR2, many of which are linked to neurological and psychiatric disorders." (PMID 40756990, 2025).
neurodevelopmental disorder (4 papers, 2024 to 2026). A behavioral and cognitive disorder with onset during the developmental period that involves impaired or aberrant development of intellectual, motor, or social functions. "Monoallelic de novo missense variants in GABBR1 and GABBR2, which encode the receptor subunits, have been associated with neurodevelopmental disorders." (PMID 41803176, 2026). "GABBR1 is an important receptor for gamma-aminobutyric acid (GABA), functional impairment of GABA receptors is associated with neurodevelopmental disorders, and GABA alterations are widely present in many regions and areas of the autistic brain." (PMID 39038939, 2024).
brain disorder (1 paper, 2016). A disease affecting the brain or part of the brain. "The expression of GABBR1 is widely studied in relation with brain disorders." (PMID 27050411, 2016).
GABBR1 also shares sentences with these, for which no sentence is quoted: encephalitis (12 papers); Gaucher disease (7); autoimmune encephalitis (6); infection (6); lysosomal storage disorders (4); alcohol use disorder (3); Cognitive impairment (3); glioblastoma (3); neurologic disease (3); pancreatic cancer (3); small cell lung carcinoma (3); Alzheimer disease (2); amnesia (2); anemia (2); anterior uveitis (2); cerebellar ataxia (2); cholangiocarcinoma (2); Global developmental delay (2); HCMV infection (2); Hyponatremia (2); infantile spasms (2); memory impairment (2); metabolic disorders (2); multiple sclerosis (2); Parkinson disease (2); pregnancy (2); Splenomegaly (2); Thrombocytopenia (2); Tinnitus (2); AIDS (1).
A further 57 diseases each share a sentence with GABBR1 in 1 paper.